BRCA1 (BRCA1 DNA repair associated)
Diseases named in the same sentence as BRCA1 in open-access papers (continued):
Sharing a sentence is not in itself a finding about the gene and the disease.
breast cancer (continued). "BRCA1, BRCA2 and CHEK2 are known breast cancer predisposition genes." (PMID 29678143, 2018). "Patients with hereditary risk variants in BRCA1, BRCA2 or other core breast cancer risk genes may be offered bilateral subcutaneous mastectomy and ovarectomy." (PMID 30190792, 2018). "According to recent studies, the presence of ovarian cancer in personal or family history of pathogenic BRCA1 founder-negative breast cancer patients increases the possibility of carrying previously undetected pathogenic BRCA1/2 non-founder mutations." (PMID 29928469, 2018). "Breast cancer occurrence was observed in two BRCA1/2 non-mutation carriers (2/650.7 person-years, 0.33%/year)." (PMID 29176636, 2018). "We report in this paper that estrogen enhances the number of breast CSCs in Brca1-deficient, ER-negative mammary tumors independent of ER." (PMID 29996906, 2018). "Note that the BRCA1/BARD1 ubiquitin E3 ligase generates K6 chains, and thus, palbociclib‐dependent reduction in K6 chains could be relevant for BRCA1 mutant breast cancers." (PMID 29669860, 2018). "Women with germline BRCA1 or BRCA2 mutations are recommended to undergo prophylactic bilateral salpingo-oophorectomy (RRSO) to reduce their risk of developing ovarian cancer (and breast cancer), usually by age 40 or after the completion of childbearing." (PMID 29389895, 2018). "We cannot exclude a possibility of an association between T-cell leukemia and BRCA2 in our patient- in a recent prospective study of 7243 women with a BRCA1 or a BRCA2 mutation a higher risk of developing leukemia among women with a BRCA2 mutation and breast cancer was reported." (PMID 30286154, 2018). "In the advanced setting, anthracycline-based regimen was associated with a non-significant trend toward a lower risk of progression in BRCA1/2-associated breast cancer compared to sporadic breast cancer." (PMID 30544963, 2018). "We also identified CHEK2 c.1111C > T variants in 2.5% (3/120) of Korean breast cancer patients without BRCA1/2 mutations." (PMID 29338689, 2018). "The cohort consisted of patients without and with a family history of breast cancer including BRCA1-mutation carriers." (PMID 29849944, 2018). "More recently, trabectedin, a marine-derived tetrahydroisoquinoline currently produced by chemical synthesis and approved for treating soft tissue sarcoma and relapsed platinum-sensitive ovarian cancer, was evaluated in BRCA1/2 carriers with advanced breast cancer." (PMID 30544963, 2018). "Therefore, we added breast cancer expression profiles from The Cancer Genome Atlas (TCGA) database to select the genes showing highly correlated expression with BRCA1." (PMID 29757984, 2018). "No studies have properly assessed PFS that is specific to breast cancer patients with BRCA1 mutations receiving only neoadjuvant platinum-based chemotherapy without adjuvant treatment." (PMID 29719582, 2018). "However, in a cohort of 17 breast cancer patients who were tested positive for BRCA1 methylation in our previous study, four patients (23.5%) were found to be positive for MGMT methylation." (PMID 30049288, 2018). "Reduction or absence of BRCA1 in breast cancer occurs through several mechanisms including hypermethylation of the BRCA1 promoter, loss of heterozygosity, and transcriptional regulation of BRCA1." (PMID 30186165, 2018). "We previously discovered that deletion of cell cycle inhibitors p16Ink4a (p16) or p18Ink4c (p18) is required for development of Brca1-deficient basal-like mammary tumors, and that mice lacking p18 develop luminal-type mammary tumors." (PMID 29996906, 2018). "Five patients had a family history of breast cancer, but none of the four patients who underwent genetic testing had germline BRCA1 or BRCA2 gene mutations." (PMID 29304773, 2018).
breast cancer (continued). "In this study, we explored the relationship between a medullary phenotype in a series of breast cancer patients without known positive family history and BRCA1/2 mutation status with next-generation sequencing (NGS) technology." (PMID 29453630, 2018). "The role of disrupted activity of the protein BRCA1 in the progression of breast cancer has been clarified, suggesting that targeting another protein with which it interacts could offer a new route to treatment." (PMID 30327455, 2018). "Four genes (six associations: BRCA1, BRCA2, and ANK2 in ovarian cancer, BRCA1, BRCA2, and ATM in breast cancer) were significant in at least one individual cancer type (FDR = 0.2, referred to as ‘individual cancer ALFRED genes’) and all four genes were also significant in the pan-cancer analysis." (PMID 29973584, 2018). "Accumulating studies propose RBBP8, known to encode the endonuclease CtIP, as a novel susceptibility gene whose functional loss increases sensitivity towards PARP1 inhibition similar to BRCA1 inactivation as, for instance, recently demonstrated in a mice xenograft model of breast cancer." (PMID 29445424, 2018). "Notably, the mother of a BRCA1 woman carrier was a breast cancer patient who was positive for methylated MGMT." (PMID 30049288, 2018). "Moreover, BARD1 and BRCA1 were positively correlated with p-AKT expression in primary and metastatic breast cancer samples, suggesting that BARD1/BRCA1 expression is associated with PI3K pathway activation." (PMID 29686231, 2018). "Occult carcinoma occurred in 75% of patients with a personal history of breast cancer and a BRCA1 pathogenic mutation, although this was not a significant result because of the small number of cases." (PMID 29507815, 2018). "Although tamoxifen has been shown by us and by others to reduce the risk of contralateral breast cancer by about 50% in BRCA1 mutation carriers, this drug has not been validated for primary prevention in this population." (PMID 30572612, 2018). "Thus, our results open up avenues to the possibility of targeting CCL5 and Ezrin as a strategy to inhibit the effect of MAF on metastasis, predominantly in BRCA1 defective breast cancers." (PMID 30224826, 2018). "Furthermore, the biological pathways ‘Role of BRCA1, BRCA2 and ATR in Cancer Susceptibility’ and ‘Breast Cancer’ were found in the top enriched terms for NA and SA regions with a p of 1.074×10−8 (2.09×10−10) and 2.804×10−5 (2.69×10−3), respectively." (PMID 30263132, 2018). "However, there has been conflicting reports regarding the subcellular localisation of the BRCA1 protein in breast cancer cells." (PMID 30323899, 2018). "However, to date, the role of BRCA1 interactions at specific stages in the progression of mammary tumors, particularly in relation to cell cycle regulation, remains elusive." (PMID 30327455, 2018). "The frequency of BRCA1 gene allelic loss were reported to be more frequent in ER negative than in ER positive sporadic breast cancer cases (39 vs 12%)." (PMID 29453630, 2018). "Distribution of age at onset of breast cancer with/without BRCA1/2 mutations shows that BRCA1/2MUT+ breast cancer occurred at a younger mean age (41.7 years) than did BRCA1/2MUT− breast cancer (45.8 years)." (PMID 30203341, 2018). "However, published evidence for BRCA1 and BRCA2 pathogenic mutation carriers (with a very high lifetime risk of breast cancer) is conflicting." (PMID 29116468, 2018). "Medical surveillance for BRCA1/2 heterozygotes reduces the risk of dying from breast cancer, however it is unlikely to affect the ovarian cancer related mortality." (PMID 30211169, 2018).
breast cancer (continued). "As expected in samples from the general population, the known risk factors for rare early-onset breast cancer (BRCA1/2672/675, HER22064, RB15925) do not show association and many receptor-related genes are absent in ER− populations." (PMID 29965997, 2018). "To investigate whether the effects could be replicated in breast cancer cells, we used short interfering RNA (siRNA) to downregulate endogenous BRCA1 in ER-positive MCF7 and T47D breast cancer cell lines which have relatively high abundance of BRCA1." (PMID 30323899, 2018). "For first breast cancers, the average age of onset in the BRCA1- and BRCA2-positive groups (90 and 98 cases) and BRCA-negative group (588 cases) was 40.2 years (95% confidence interval (CI) 38.15–42.25), 41.7 years (95% CI 39.71–43.70), and 45.4 years (95% CI 44.54–46.26), respectively." (PMID 29176636, 2018). "Based on our results showing FADD as a BRCA1 target, we further examined whether this finding is valid in breast cancer patients." (PMID 29757984, 2018). "Two studies have investigated the breast cancer risk in Asian women with BRCA1/2 mutations, and no published estimates are available for ovarian cancer." (PMID 29861850, 2018). "MBD2 has regulatory role in BRCA1 gene expression and could be used as biomarker for breast cancer and targeted by drug combination therapy." (PMID 29460395, 2018). "We present here, that miRNAs deregulated following Brca1 loss may be useful as prognostic markers in patients with basal-like breast cancer or tumours arising in BRCA1 mutant carriers." (PMID 30323900, 2018). "We aimed to identify novel genetic variants in prospectively detected breast cancer (BC) or gynecological cancer cases tested negative for their families’ pathogenic BRCA1/2 variant (path_BRCA1 or path_BRCA2)." (PMID 29371908, 2018). "BRCA1 and BRCA2 mutations comprise 32 to 82% of hereditary breast cancer cases." (PMID 29720094, 2018). "Inactivating mutations of BRCA1 and BRCA2 frequently occur in breast cancer as well, while unique mutations in GATA3, PIK3CA, and MAP3K1 are enriched in the luminal A subtype of breast cancer." (PMID 29753129, 2018). "In breast cancer for example, mutations in the BRCA1 and BRCA2 genes are more commonly found, with one Nigerian study identifying mutation rates of 7.9% for BRCA1 and 3.1% for BRCA2—far higher than in the cancer genome atlas (TCGA), where these are 1.3 and 1.5% respectively." (PMID 30234014, 2018). "However, a recent systematic review showed that both BRCA1 and BRCA2 mutation carriers had significantly worse breast cancer specific survival." (PMID 29566657, 2018). "Interestingly, the fold change of the BRCA1 expression level in breast cancer patients highly correlated (R = 0.89) with patient’s age in eight out of nine cases." (PMID 30049288, 2018). "All six breast cancer patients in our study with proven pathogenic non-founder BRCA1/2 mutations had a triple-negative phenotype." (PMID 29928469, 2018). "Breast cancers arising from BRCA1/2 germline mutation carriers are associated with a lack of expression and/or function of the corresponding protein, which induces genomic instability." (PMID 30544963, 2018). "Two prior studies have reported worse prognosis in male breast cancer patients with a deleterious BRCA1/2 mutation compared to those without a mutation." (PMID 29433453, 2018). "We found no clear evidence that either BRCA1 or BRCA2 germline mutations significantly affect overall survival with breast cancer after adjusting for known prognostic factors." (PMID 29337092, 2018). "Therefore, LYN kinase depletion suppresses Brca1 mammary tumor cell growth both in vitro and in vivo." (PMID 30590041, 2018). "Not all breast cancers in a family are an alert for special attention, but we know that those achieving younger women and presenting some mutations, such as in BRCA1 and 2 genes flag other close family women to pay more attention to preventive care." (PMID 30627525, 2018).
breast cancer (continued). "They included 1380 women with a BRCA1 or BRCA2 mutation with a history of breast cancer (cases) and matched them to 1380 female BRCA1 or BRCA2 mutation carriers without a history of breast cancer (controls)." (PMID 29937543, 2018). "Despite the inclusion of an older population in the current study, one cannot preclude a potential breast cancer protective effect of denosumab (or other RANKL inhibitors) in younger high-risk populations, particularly among women with an inherited BRCA1 mutation." (PMID 30420611, 2018). "BRCA1/2 breast cancer proteins are key players in HR via their mediation of RAD51 nucleofilament formation and function; however, their individual roles and crosstalk in vivo are unknown." (PMID 30250272, 2018). "Accordingly, in the current study, the BRCA1 mRNA expression was compared in the setting of triple-negative and luminal tumors, and clinicopathological significance of BRCA1 expression was evaluated in Iranian breast cancer patients." (PMID 28646826, 2018). "In a study of human breast cancer where RAS mutations are rare, high KSR1 levels were shown to correlate with overall survival, and mechanistic studies suggested that this is due to KSR1 stabilization of BRCA1." (PMID 29596465, 2018). "Samples from 120 patients who were negative for BRCA1/2 mutations, but had been diagnosed with breast cancer that was likely hereditary, were prospectively evaluated for the prevalence of high-penetrance and moderate-penetrance germline mutations." (PMID 29338689, 2018). "We next assessed whether the PIN1-LYN regulatory mechanism is likely to be more widely applicable than just to BRCA1 breast cancer." (PMID 30590041, 2018). "Mutations in the BRCA1 and BRCA2 genes account for 60–80% of inherited breast cancers." (PMID 29733510, 2018). "In conclusion, our study demonstrates that EDC4 functionally phenocopies BRCA1, playing a role in HR-mediated DNA repair by regulation of end resection, and that germline mutations in EDC4 may confer risk of breast cancer." (PMID 29511213, 2018). "The cytoplasmic localization of BRCA1 was also confirmed in clinical specimens in a study of 103 women with breast cancer, where cytoplasmic localisation of BRCA1 was found in 51.4% of tumours and exclusive nuclear localisation was only found in a minority of cases." (PMID 30323899, 2018). "The BRCA1-related hereditary breast cancers show a trend toward triple-negative phenotype." (PMID 28646826, 2018). "In this study, we addressed the relationship between morphological medullary phenotype and BRCA1/2 somatic mutations in breast cancer without known positive family anamnesis." (PMID 29453630, 2018). "The dysregulation of BRCA1 expression induces a basal-like phenotype in breast cancer cells." (PMID 29921310, 2018). "In this report, we used p16;Brca1 and p18;Brca1 double-mutant mammary tumors and human BRCA1 mutant breast cancer patient-derived xenografts (PDX) to determine the function and mechanism of estrogen in promoting ER-negative BRCA1-deficient tumor initiation and progression." (PMID 29996906, 2018). "We further discovered that estrogen activates the Akt pathway in Brca1-deficient mammary tumor cells independent of ER, and that pharmaceutical inhibition of Akt activity suppresses EMT and cell proliferation preventing Brca1-deficient tumor progression." (PMID 29996906, 2018). "Plasma microRNA levels differed between patients with and without breast cancer, between benign disease from wildtype and BRCA1-mutation carriers and between breast cancer with and without metastases." (PMID 29849944, 2018).
breast cancer (continued). "HMMR, a breast cancer susceptibility gene in BRCA1 mutation carriers, encodes a non-integral hyaluronan receptor that promotes breast cancer migration and invasion in concert with the integral hyaluronan receptor CD44." (PMID 29566768, 2018). "BRCA1 mutation-associated breast cancer is more likely to be hormone receptor negative and have a higher grade and basal-like phenotype, while BRCA2-associated breast cancer resembles sporadic breast cancer." (PMID 30174725, 2018). "The different ratio could potentially be explained by the higher penetrance of ovarian cancer and younger age at breast cancer diagnosis in BRCA1 carriers, making those families more likely to fulfill current BRCA testing criteria." (PMID 29164420, 2018). "(2003) demonstrated that tumors arising in mutant BRCA1 carriers are predisposed to display a basal-like gene expression profile, although a majority of the breast cancers arising in carriers of a BRCA1 mutation have no unique histological features." (PMID 29874626, 2018). "Similarly, siRNA-mediated reduction of BRCA1 in breast cancer cells resulted in a decrease in ACCA phosphorylation and an increase in FASN abundance." (PMID 30323899, 2018). "In this report, case 2, with both BRCA1 and BRCA2 germline mutations, showed high response of platinum-based chemotherapy for lymph node recurrence and long-term survival after the recurrence, in a manner similar to BRCA1/2-mutated ovarian and breast cancers." (PMID 31608315, 2018). "A later age at menarche and breastfeeding are protective for BRCA1-associated breast cancer, but do not appear to influence risk in women with a BRCA2 mutation." (PMID 30572612, 2018). "Germline mutations of the BRCA1 and BRCA2 genes confer high risks of breast cancer." (PMID 29321957, 2018). "Similarly, BRCA1 and BRCA2 founder mutations account for 78% of families with hereditary breast cancer in Chile." (PMID 35693198, 2018). "Indeed, deletion of Ezh2 accelerated tumors in a mouse model of Brca1-deleted breast cancer and in a breast cancer model of Notch activation." (PMID 30080881, 2018). "IHC staining showed that the expression of BARD1 and BRCA1 was significantly increased in the recurrent tamoxifen-resistant tumors than that in primary tumors, in agreement with the finding of upregulated BARD1 and BRCA1 in tamoxifen-resistant breast cancer cell lines." (PMID 29686231, 2018). "Furthermore, we found a considerable reduction in the expression level of the BRCA1 in six out of nine breast cancer patients." (PMID 30049288, 2018). "Lack-of-function mutations in EDC4 were detected in BRCA1/2-mutation-negative breast cancer cases, suggesting a role in breast cancer susceptibility." (PMID 29511213, 2018). "The medullary phenotype of breast cancer, which is often but not exclusively encountered in BRCA1 germline mutation carriers, cannot reliably be used as an indication for genetic testing." (PMID 29453630, 2018). "Interestingly, we have also found that m6A levels in the large internal exons of LATS1 and BRCA1 are significantly lower in pPA-activated breast cancer cells relative to untransformed mammary cells." (PMID 29362392, 2018). "The role of pathogenic BRCA1/2 mutations in breast cancer is currently not linked to specific therapies and is rather restricted to the choice for genetic counseling." (PMID 29453630, 2018). "We first compared the performance of PAFA, Eigen, CADD, GWAVA, FATHMM-MKL, and DANN on prioritizing coding variants from five well-studied genes (MLL2, CFTR, BRCA1, BRCA2, and TERT) associated with Kabuki syndrome, cystic fibrosis, breast cancer, or aggressive thyroid tumor, respectively." (PMID 29996888, 2018). "We evaluated the activity of the PARPi olaparib in patient‐derived tumor xenografts (PDXs) from breast cancer (BC) patients and investigated mechanisms of sensitivity through exome sequencing, BRCA1 promoter methylation analysis, and immunostaining of HRR proteins, including RAD51 nuclear foci." (PMID 30377213, 2018).